ENSG00000285648 (lincRNA)
Gene: Long non-coding RNA gene on chromosome 17 (73,865,818 to 74,040,859, reverse strand). Ensembl gene ENSG00000285648.
Diseases named in the same sentence as ENSG00000285648 in open-access papers:
ENSG00000285648 is named in the same sentence as 8 diseases in open-access papers, as found by Europe PMC text mining. Sharing a sentence is not in itself a finding about the gene and the disease. The quoted sentences say what the papers report.
gastric cancer (1 paper, 2019). A primary or metastatic malignant neoplasm involving the stomach. "Further studies have shown that lincrna-p21 knockout can promote the malignant behavior of gastric cancer cells according to overexpression assay." (PMID 31572428, 2019).
liver fibrosis (1 paper, 2021). "At present, several lncRNAs have been proved to be involved in the occurrence and development of liver fibrosis by controlling PI3K/Akt signaling pathway, such as lincrna-p21, HOTAIR, and H19." (PMID 34597331, 2021).
ENSG00000285648 also shares sentences with these, for which no sentence is quoted: AIDS (1 paper); cancer (1); leishmaniasis (1); leprosy (1); malaria (1); tuberculosis (1).